CD68 (CD68 molecule)
Diseases named in the same sentence as CD68 in open-access papers (continued):
Sharing a sentence is not in itself a finding about the gene and the disease.
infection (continued). "While CD68 expression did not change with infection or treatment, Mtb infection resulted in the elevated expression of HLA-DR and CD200R, while activation markers such as CCR7, CD80/CD86, and CD64 as well as scavenger receptors CD163 and CD206 were reduced on Mtb-infected cells." (PMID 40305296, 2025). "Markers of infection such as CD68 cells are not consistently found in the lungs of SIDS cases." (PMID 29184885, 2017). "Skin biopsies of the SC inoculation site obtained seven days after infection with either UCD52 or UCD59 are noted for prominent neutrophilic infiltration with extensive infection of endothelial cells (CD31-positive), fibroblasts (vimentin-positive), and macrophages (CD68-positive)." (PMID 24681748, 2014). "Several infected monocytes/macrophages (CD68+) were detected surrounding blood vessels and migrating to the parenchyma (IF and TEM data), suggesting that these cells might be delivering SARS-CoV-2 to the testes (arrows), and contributing to the infection of testicular cells." (PMID 36797789, 2023). "Cells were monitored during infection and analyzed to ensure the absence of macrophage or dendritic cell markers (CD11c+, CD11b+, CD141+, CD303+, CD11b+, CD68+, CD80+)." (PMID 23717203, 2013). "Here, the expression of CD68, CD80, CD86, HLA-DR, MMR, TLR2 and TLR4 was analyzed under different experimental conditions (plus or minus exposure to CS, and with or without Mtb-infection)." (PMID 24278357, 2013). "The expression of microglial activation markers, including Iba1, CD68, and MHC-II after infection, along with the low replication levels and absence of CPE, suggests that microglia may serve as a viral reservoir and a source of inflammation in the CNS." (PMID 37376550, 2023). "At this same stage of infection, HEV antigen (HEV Ag) could be detected in all infected animals, predominantly in non-reactive Kupffer cells (CD68+iNOS-) and sinusoidal lining cells." (PMID 31211801, 2019). "The availability of validated antibodies for rhesus enabled characterization of infected leucocyte subsets, including "inflammatory" monocytes expressing CD14/CD68, dendritic cell phenotypes with CD1a/DCSIGN positivity, but no intracellular infection of T-cells, or endothelial cells was found." (PMID 29522521, 2018). "Remarkably, other than CD68 expression, human (and mouse) host cell abundance and immune responses in BLT brains were minimally affected despite variable infectious input titers and durations of infection, unlike in human brains." (PMID 29037245, 2017).
adenocarcinoma (18 papers, 2010 to 2026). A common cancer characterized by the presence of malignant glandular cells. "In subgroup analyses, adenocarcinoma NSCLC patients with high CD68 expression (log-rank p = 0.034) showed a significant survival advantage, whereas adenocarcinoma NSCLC patients with high M2 ratio (log-rank p = 0.047) had poor survival." (PMID 33228719, 2020). "In addition, when the pathology was adenocarcinoma, CD68‐positive macrophages showed a strong tendency to occupy the larger SCS of any node (p = 0.049)." (PMID 40151162, 2025). "Using RNAscope, a novel ISH method, we confirmed the similarities between EOC and fallopian tube, normal and adenocarcinoma using FOLR1, FOLR2, CD68 and CD11b markers." (PMID 25971554, 2015). "Positive; CD204+: CD68+ macrophage ratio increased in PIN and adenocarcinoma compared to benign tissue." (PMID 26217583, 2015). "In the GC sample cohort from the TCGA (Stomach adenocarcinoma (TCGA, Firehose Legacy, n = 478)), the levels of several markers for macrophages (FN1, MRS1, CD68, and CCL7), blood vessels (CDH5) and lymphatic vessels (VEGFC) exhibited positive correlations with TGM2 expression." (PMID 32467608, 2020). "Immunohistochemical and morphometric analyses were performed to examine DC‐SIGN‐, CD68‐, and CD169‐positive cells in the subcarinal node (proximal) and paratracheal nodes (distal nodes) from 16 patients with lower‐lobe lung cancer without metastasis (adenocarcinoma, 11; squamous, 5)." (PMID 40151162, 2025).
neurodegenerative disease (12 papers, 2015 to 2025). A disorder of the central nervous system characterized by gradual and progressive loss of neural tissue and neurologic function. "Decreased expression of pro-inflammatory genes, which are associated with neurodegenerative disease or astrocyte and microglia phenotypes Cd40, C1qB, Cd68, Cd45, Aqp-4, Il1α, Fkbp5, Ggta1, Cd16, H2-T23, and Serping1, was observed following C-32:6 treatment and C1qC, Tspo, and Gbp2 with FFA C-34:6." (PMID 37740008, 2023). "CD68 is indicative of the microglial response to various pathological conditions, including neurodegenerative diseases and infections." (PMID 40349778, 2025). "It has been shown that microglia with low IBA-1 and high CD68 expression are related to neurodegenerative diseases and aging." (PMID 36275769, 2022). "Immunohistochemistry studies typically report alterations in morphology and increased immunoreactivity for markers such as CD68 and HLA-DR as evidence of microglial activation in neurodegenerative diseases." (PMID 35933388, 2022). "Cluster of differentiation protein 68 (CD68) is a cell surface marker for microglial activation often used in mouse models of neurodegenerative disease." (PMID 36369162, 2022). "The reduction in CD68 immunoreactivity between sedentary and exercised Grn−/− mice is consistent with the general anti-inflammatory effects of exercise, including those found in other mouse models of neurodegenerative disease." (PMID 26361634, 2015). "Histologic sections of the brainstem showed marked pallor of the corticospinal tracts bilaterally on Luxol fast blue stain with microgliosis on CD68 immunohistochemistry that was greater than in a control without neurodegenerative disease." (PMID 36895955, 2023).
kidney diseases (11 papers, 2016 to 2026). "CD68 serves as a marker for macrophages and plays a significant role in the development of numerous renal disorders, especially when pro-inflammatory cytokines such as TNF-α and IL-1β are present." (PMID 40529491, 2025). "CD68+ macrophages were positively related with the Scr, 24-h proteinuria, process of renal disease, and a worse outcome.The number of macrophages that increased in the tubulointerstitium was regarded as the predictor for poor prognosis in IgAN patients." (PMID 37529043, 2023). "The frequency of HLA-DR+, CD14+, CD16+ and CD68+ cells were all significantly increased in patients with HFRS as compared to patients with other kidney diseases." (PMID 33690725, 2021). "Biopsies from a cohort of 58 patients with various forms of kidney disease were examined for MMT cells that co-express macrophage (CD68) and myofibroblast (α-smooth muscle actin, α-SMA) markers." (PMID 27906172, 2016). "To identify MMT cells in human kidney disease, we sought to detect cells that express both macrophage (CD68) and myofibroblast (α-SMA) markers." (PMID 27906172, 2016). "Glomerular CD68+ cell counts could be promising predictors of kidney disease progression among patients with DN and may shed light on new treatment pathways." (PMID 40338344, 2025). "Glomerular CD68+ cell count may serve as a promising predictor of kidney disease progression among patients with DN." (PMID 40338344, 2025). "The increase in CD68-positive macrophage densities in both the cortex and medulla were found to have strong positive correlation with cortical scarring in the tubuo-interstitial region in several native kidney diseases in human studies." (PMID 38612574, 2024). "Although kidney diseases are of vastly different etiology and pathogeneses, a common feature is the infiltration of the affected renal tissue compartment by inflammatory cells, among which macrophages—detected by their markers CD68, CD14, and CD163—are a significant component." (PMID 38612574, 2024). "In a study of 204 patients with IgAN, the presence of CD68+ (a marker of pan-macrophage or M1 type) macrophages was positively correlated with the following: Serum creatinine at the time of biopsy, proteinuria, progression of renal disease, and a worse disease outcome." (PMID 35601494, 2022). "We stained a unique set of bouin-fixed paraffin-embedded kidney biopsies from 37 patients with acute HFRS and 43 patients with other kidney diseases (controls) for HLA-DR, CD14, CD16 and CD68." (PMID 33690725, 2021).
inflammation (9 papers, 2019 to 2024). Aberrant reaction of the microcirculation characterized by movement of fluid and leukocytes from the blood into extravascular tissues. "In vivo, due to the higher match of CD68 with iNOS in LPS group, we concluded that during acute lung inflammation, the M1-type macrophages would be absolutely dominant, which had a strong staining and thus led to the CD68 and iNOS duplicate positive staining." (PMID 34122107, 2021). "Immunochemical analysis CD68 staining further displayed that monocyte/macrophages are remarkably increased in Mic19 LKO mouse (3 months old) liver, confirmed that Mic19 LKO causes chronic hepatic inflammation in mice at 3 months old." (PMID 38168065, 2024). "We found a significant positive correlation between the influx of macrophages (CD68+) in the orbital tissue and serum LBP level (r = 0.4, p = 0.043), linking a “leaky” gut with orbital inflammation." (PMID 38107520, 2023). "Notably, resident CD68+ macrophage populations express hPGDS at even higher levels than mast cells, as estimated by immunofluorescence staining, emphasizing that resident macrophages likely contribute to elevated PGD2 levels in acute lung inflammation." (PMID 34769126, 2021).
bacterial infection (8 papers, 2012 to 2025). "Although further studies are required to elucidate the precise role of CD68+ Kupffer cells in various immune phenomena, including hepatocyte regeneration, it should be kept in mind that the depletion of CD68+ Kupffer cells made mice extremely susceptible to bacterial infection." (PMID 26333171, 2015). "Consistently, IL-26 produced by CD68+ alveolar macrophages and Th17 cells has been shown to strengthen pulmonary antimicrobial immunity by promoting neutrophil recruitment to sites of bacterial infection." (PMID 41516201, 2025). "The aim of the present study was to evaluate the influence of a modified mesh structure with variation in filament linking on the occurrence of bacterial infection that is indicated by the occurrence of CD68+, CD4+, and CD8+ cells in two different materials." (PMID 37509722, 2023). "Furthermore, IL-26 produced by CD68+ alveolar macrophages and Th17 cells strengthens antimicrobial defense in the lungs by promoting neutrophil recruitment to sites of bacterial infection." (PMID 41516201, 2025). "There was an increase in the percentage of innate immune system cells such as CD68+ macrophages, ICAM-1-expressing cells, and CD54+ dendritic and endothelial cells, which is a normal response to bacterial infection." (PMID 35625758, 2022).
kidney (7 papers, 2018 to 2023). "Expression levels of acute kidney injury markers Kim1 and Lcn2, and cytokines Ccl2 and Cd68, were lower in the cisplatin-injected Dpep1+/− mice when compared to wild-type littermates." (PMID 34426578, 2021). "Dermal inflammation was evidenced by a significantly increase of CD68 + macrophages throughout the dermal tissue in kidney patients compared to healthy donors (p = 0.01)." (PMID 30885222, 2019).
inflammatory myopathies (6 papers, 2018 to 2025). "Macrophage markers (CD14, CD68) were also upregulated, at levels similar to those seen in other inflammatory myopathies." (PMID 41441888, 2025). "In anti-HMGCR myopathy, most of the inflammatory infiltrate in the muscle histology is composed of CD68+ macrophages." (PMID 40225087, 2025). "As expected, macrophage markers (CD14 and CD68) were upregulated at higher levels than in other inflammatory myopathies." (PMID 40568658, 2025). "Both the absolute numbers of CD68+ and CD163+ cells, and the ratio of CD163+ and CD68+ cells, were higher in the groups with inflammatory myopathies, compared to controls." (PMID 32936839, 2020). "In this study, the CD163+ macrophages constituted a small fraction of all macrophages (CD68+) in control muscle, but their relative ratio to CD68+ macrophages was increased in inflammatory myopathies." (PMID 32936839, 2020). "Although the presence of the CD68+ infiltrate in the skin may support this drug-induced myopathy, further studies are needed." (PMID 40225087, 2025).
neurological diseases (6 papers, 2018 to 2023). "The level of CD68 expression is nearly undetectable in microglia of normal brain, but is frequently induced following seizures and other neurologic disorders." (PMID 33472865, 2021). "In addition, increases in CD-68 and GFAP which are markers of microglia and astrocytes are seen in neurological diseases and may contribute to the inflammation and disease." (PMID 33396967, 2020).
head and neck tumors (5 papers, 2018 to 2021). "We analysed 549 1.5 mm × 1.5 mm regions of interest (ROIs), taken from 16 human head and neck tumour slides stained to show macrophage locations (CD68+)." (PMID 33122646, 2020). "In this study, we showed that CD68+ macrophage infiltration significantly increases during head and neck tumor progression, both in the intra-epithelial compartment and in the stromal compartment." (PMID 29541395, 2018). "In conclusion, we demonstrate for the first time that CD68+ macrophage infiltration increases during head and neck tumor progression, both in the intra-epithelial and in the stromal compartment." (PMID 29541395, 2018). "As recently documented in a methodological study based on CD68-positive macrophages within human head and neck tumors, combinations of spatial statistics-derived parameters can lead to better predictions of macrophage infiltration than any classical morphometric method." (PMID 33959827, 2021). "Therefore, we analyze the spatial patterns of CD8+, FoxP3+, and CD68+ cells across whole slide images taken from 16 head and neck tumors." (PMID 34625491, 2021). "The association of infiltrating macrophages with a poor prognosis, demonstrated by CD68 and/or CD163 immunophenotyping, has been previously reported in a number of head and neck tumours, but infrequently in selective series of OP-SCCs." (PMID 33769181, 2021).
heart (4 papers, 2016 to 2020). "Acute rejection in heart transplant recipients was associated with severe fibrosis in 1-year biopsies, which was associated with higher CD68+CD163+ M2 macrophages compared to barely present CD68+CD80+ M1 macrophages in graft." (PMID 33329555, 2020). "Simple STRDD is an unknown benign neoplasm and is mainly confirmed by pathological examinations, showing positive for S-100 protein and CD68, and negative for CD1a." (PMID 27442634, 2016).
metabolic disorders (4 papers, 2015 to 2023). "Under the stimulus of metabolic disorders, Mφ polarized from anti-inflammatory M2-like macrophages (CD68+/Arg-1+) to pro-inflammatory M1-like macrophages (CD68+iNOS+)." (PMID 37904236, 2023).
psychiatric diseases (3 papers, 2019 to 2021). "Of note, plasma dilution might be also clinically relevant to the attenuation of hyper-activated CD68+ microglia in psychiatric diseases, where neuroinflammation is implicated in pathology." (PMID 33191466, 2021). "While the role of microglial phagocytosis in mental illnesses remains elusive, we previously found that R-SDS increased the signals of CD68, a marker for phagocytic activity, in the prefrontal microglia in a manner correlated to the level of social avoidance." (PMID 31505850, 2019).
cardiac disease (2 papers, 2015 to 2024). "Inflammation has been closely associated with heart disease, and CD68 staining used in this study demonstrated significant macrophage infiltration in Tg myocardium following AngIV stimulation, but not before." (PMID 26092119, 2015).
cardiovascular disease (2 papers, 2012 to 2025). "The upregulation of CD68 is associated with increased myocardial inflammation and fibrosis, indicating its significant role in maternal obesity-induced cardiovascular disease in offspring, particularly during macrophage-mediated inflammatory responses and tissue damage." (PMID 41007990, 2025). "The obese CAD patients with a waist circumference greater than the cut-off values (cut-off points of waist circumference for cardiovascular disease risk were 87 cm for men and 83 cm for women) had increased levels of C:18:4n-3, CD68, 11β-HSD-1 and GCR in MAT (p < 0.05, respectively)." (PMID 23009206, 2012).
colonitis (2 papers, 2020 to 2025). "Berberine can reduce the expression of pro-inflammatory cytokines IL-1, IL-6 and TNF- mRNA and CD68(markers of macrophages) in MICE with DSS-colonitis." (PMID 33019433, 2020). "Fourth, the prognostic significance of CD68 may vary across different digestive system cancer subtypes and stages, necessitating validation in larger, multi-center cohorts with standardized clinical annotations." (PMID 40918116, 2025).
haematological diseases (2 papers, 2021 to 2025). "The perivisceral lymph nodes appeared subverted from predominantly atypical epithelioid or sarcomatoid medium-sized cells that were CD68- and lysozyme-positive, as well as CD45RO, typical markers in the differential diagnosis with other haematological diseases." (PMID 34948520, 2021).
peripheral neuropathy (2 papers, 2022). A disorder affecting the peripheral nervous system. "Previous reports have shown that CD68-positive macrophages were activated on the sural nerves of patients with MPA with peripheral neuropathy, and IL-6 was overexpressed by CD68-positive macrophages in sural nerve specimens of vasculitic neuropathy." (PMID 36362162, 2022).
brain disease (1 paper, 2009). "Finding these cells in the brain at the same frequency as in the spleen and lymph nodes highlights the importance of the frequency and potential importance of CD68 macrophages in the pathogenesis of brain disease." (PMID 19333384, 2009).
infectious disease (1 paper, 2017). A disorder directly resulting from the presence and activity of a microbial, viral, or parasitic agent in humans. "The immunohistochemistry results suggested that these cells were S-100-positive, CD68-positive, and CD1a-negative; staining with GMS and PAS was negative, thereby excluding infectious diseases, which aids in differentiating RDD from other diseases." (PMID 28770226, 2017).
intestinal diseases (1 paper, 2025). "The level of the macrophage marker CD68 corresponds with the degree of inflammation in intestinal diseases." (PMID 40453351, 2025).
vasculopathy (1 paper, 2020). "Besides allograft-vasculopathy, we could also show the immigration of immunological relevant cells, such as CD4- and CD68-positive-cells but also their deteriorating effects on muscle tissue." (PMID 32589662, 2020).
CD68 also shares sentences with these, for which no sentence is quoted: idiopathic pulmonary fibrosis (5 papers); allergic asthma (3); anemia (3); bladder tumors (3); ductal carcinoma in situ (3); esophageal squamous cell carcinoma (3); hyperuricemia (3); AL amyloidosis (2); benign granular cell tumor (2); benign ovarian tumor (2); biliary atresia (2); cardiac sarcoidosis (2); cerebral infarct (2); chronic obstructive pulmonary disease (2); coronary artery disease (2); cutaneous T cell lymphoma (2); dermatofibrosarcoma protuberans (2); end-stage renal disease (2); ganglionitis (2); germ cell tumor (2); gestational diabetes (2); glomerular disease (2); gout (2); granuloma annulare (2); hemophagocytic lymphohistiocytosis (2); Huntington disease (2); Hypercholesterolemia (2); influenza (2); interstitial lung disease (2); laryngeal carcinoma (2).
A further 206 diseases each share a sentence with CD68 in 2 papers or fewer.